ZNF93 (zinc finger protein 93)
Description:
Transcription factor specifically required to repress long interspersed nuclear element 1 (L1) retrotransposons: recognizes and binds L1 sequences and repress their expression by recruiting a repressive complex containing TRIM28/KAP1. Not able to repress expression of all subtypes of L1 elements. Binds to the 5' end of L1PA4, L1PA5 and L1PA6 subtypes, and some L1PA3 subtypes. Does not bind to L1PA7 or older subtypes nor at the most recently evolved L1PA2 and L1Hs. 50% of L1PA3 elements have lost the ZNF93-binding site, explaining why ZNF93 is not able to repress their expression.
Synonyms: ZNF505; HPF34; TF34; FLJ12488; HTF34
Tractability: PROTAC: ubiquitination databases record sites on it.
Gene: Protein-coding gene on chromosome 19 (19,900,913 to 19,963,464, forward strand). Ensembl gene ENSG00000184635.
Subcellular location: Nucleus
Pathways (Reactome):
Gene expression (Transcription): Regulation of endogenous retroelements by KRAB-ZFP proteins
Gene Ontology:
Molecular function: DNA-binding transcription repressor activity, RNA polymerase II-specific; DNA-binding transcription factor activity; DNA-binding transcription factor activity, RNA polymerase II-specific; RNA polymerase II cis-regulatory region sequence-specific DNA binding; zinc ion binding
Biological process: transposable element silencing; regulation of transcription by RNA polymerase II; negative regulation of transcription by RNA polymerase II; regulation of DNA-templated transcription
Cellular component: nucleoplasm; nucleus
Genetic constraint (gnomAD): Loss-of-function variants: 31 observed, 45.99 expected, observed/expected ratio (o/e) 0.67, 90% interval 0.51 to 0.91. The upper end of that interval is the gene's LOEUF score, 0.91, which puts it in group 3 of 6, group 1 being the genes least tolerant of losing a copy. Missense variants: 565 observed, 705.38 expected, observed/expected ratio (o/e) 0.8, 90% interval 0.75 to 0.86. Synonymous variants: 217 observed, 235.37 expected, observed/expected ratio (o/e) 0.92, 90% interval 0.82 to 1.03.
Homologues: Orthologues: chimpanzee ZNF93 (99% identical), macaque ZNF93 (84% identical). Paralogues in human: ZNF254 (67% identical), ZNF726 (67% identical), ZNF724 (66% identical), ZNF728 (64% identical), ZNF681 (64% identical), ZNF85 (63% identical), ZNF708 (63% identical), ZNF429 (63% identical), ZNF43 (60% identical), ZNF676 (59% identical), ZNF493 (58% identical), ZNF90 (57% identical), and 164 more.
Diseases named in the same sentence as ZNF93 in open-access papers:
ZNF93 is named in the same sentence as 9 diseases in open-access papers, as found by Europe PMC text mining. Sharing a sentence is not in itself a finding about the gene and the disease. The quoted sentences say what the papers report.
ovarian carcinoma (3 papers, 2009 to 2022). A malignant neoplasm originating from the surface ovarian epithelium. "Evidence shows that ZNF93 upregulation in cisplatin‐resistant ovarian cancer cell lines is associated with low survival, and its knockdown enhanced sensitivity to cisplatin." (PMID 35810383, 2022). "The Zinc-fingers and homeoboxes 3 (ZHX3) and ZNF93 had been reported to be significantly increased and were associated with poor prognosis in gastric cancer 22 and ovarian cancer 23, respectively." (PMID 33976729, 2021). "ZNF93 was overexpressed in two ET-743 resistant Ewing sarcoma cell lines as well as in a cisplatin resistant ovarian cancer cell line, but was not overexpressed in paclitaxel resistant cell lines." (PMID 19742314, 2009).
chondrosarcoma (1 paper, 2009). A malignant cartilaginous matrix-producing mesenchymal neoplasm arising from the bone and soft tissue. "Importantly, overexpression of the ZNF93 protein in a PM00104 and ET-743 sensitive chondrosarcoma cell line CS-1 led to a modest level of PM00104, ET-743 and cisplatin resistance implying an important role for ZNF93 in the development of the drug-resistant phenotype." (PMID 19742314, 2009).
lung carcinoma (1 paper, 2025). "It has been indicated that there is a robust correlation between the ZNF93 gene and the susceptibility to lung cancer; however, the precise mechanisms by which it exerts its influence during the initiation and progression of lung cancer are not yet fully understood." (PMID 40647501, 2025).
melanoma (1 paper, 2023). A malignant, usually aggressive tumor composed of atypical, neoplastic melanocytes. "The heatmap was used to demonstrate the expression levels of the genes TBX21, ZNF799, HEY2, ZNF580, IRF4, CREB3, and ZNF93 during the pseudotime trajectories of four distinct subtypes of melanoma cells." (PMID 37435067, 2023). "In addition, the expression of ZNF93 and TBX21 in C4 melanoma CORO1A most significantly differed between other melanoma subtypes." (PMID 37435067, 2023).
cancer (2 papers, 2009 to 2025). A tumor composed of atypical neoplastic, often pleomorphic cells that invade other tissues. "Lastly, ZNF519 ranked fourth behind ZNF695, ZNF724P, and ZNF93 among KZFPs whose expression correlated positively with proliferation across 33 TCGA cancer types, pointing toward a general association between proliferation, i.e., repeated cell cycling, and elevated ZNF519 expression." (PMID 40555235, 2025). "Our analyses of endogenous ZNF93 expression demonstrated that ZNF93 is frequently upregulated in ET-743, PM00104 and cisplatin multiple drug resistant cancer cell lines, ZNF93 down-regulation by siRNA could partially recover sensitivity to ET-743,PM00104 and cispatin." (PMID 19742314, 2009).
Tumor (2 papers, 2009 to 2025). "Further studies on tumor samples to correlate the levels of zinc finger protein such as ZNF93 and DNA repair genes with clinical data will further clarify the biochemical roles of these proteins and their potential as therapeutic targets." (PMID 19742314, 2009). "Tumor specimens exhibited elevated expression of DTX2, SALL1, ZNF93, ZNF146 and ZSCAN16, contrasting with reduced levels of EGR2, GATA2, and ZEB2." (PMID 40647501, 2025).
ZNF93 also shares sentences with these, for which no sentence is quoted: breast carcinoma (1 paper); Ewing sarcoma (1); gastric cancer (1).